RIPK1 (receptor interacting serine/threonine kinase 1)
Diseases named in the same sentence as RIPK1 in open-access papers (continued):
Sharing a sentence is not in itself a finding about the gene and the disease.
cancer (continued). "Necrostatin-1s, GSK2982772, and 1-methyl-D-tryptophan did not block the decrease in cell viability induced by sulfasalazine, indicating that necrostatin-1 could inhibit ferroptotic cell death in a RIPK1- and IDO-independent manner in some populations of cancer cells." (PMID 34572979, 2021). "However, the expression of RIPK1, RIPK3, and MLKL has been found to be upregulated in some cancers (i.e., glioblastoma, pancreatic, lung, and esophageal cancer), in which a high activation of the necroptotic cascade seems to be correlated with a poorer prognosis in different studies." (PMID 32326539, 2020). "In addition, whether RIPK1 and its interplay with TLR3 could play a role in CCA and regulate cancer cell invasion have also remained largely unknown." (PMID 33036630, 2020). "However, the downregulation of necroptotic factors may not occur in all cancers: high expression of RIPK1 or MLKL has been reported to predict worse prognosis for some cancer patients, both in melanoma and breast tumors." (PMID 37628814, 2023). "The fact that supports this view is that DAMPs released by necroptosis of cancer cells alone are not sufficient for CTL cross‐initiation, but are required for cellular transcription through RIPK1 signalling and NF‐κb in dying cells." (PMID 38652105, 2024). "It is not surprising that RIPK1, RIPK3, and MLKL in cancer play a central role in modulating necroptosis." (PMID 33567618, 2021). "The inhibition of necroptosis through downregulation of its main driver (RIPK1, RIPK3, and MLKL) has been observed in different cancer types, showing in some cases also a negative impact on patient survival." (PMID 34745951, 2021). "On the contrary, the use of TAK1 and RIPK1 kinase inhibitors in our in vitro experiments suggested that the lack of TAK1-mediated negative regulation on RIPK1 kinase activity was primarily responsible for PCD induction during ADM and likely prevented cancer development in KRASG12D TAK1ΔAC mice." (PMID 39971907, 2025). "Caspase inhibitor and/or second mitochondria-derived activator of caspase mimetic, which sensitize cells to RIPK1- and RIPK3-dependent necroptosis downstream of tumor necrosis factor receptor-like death receptors, also did not alter the response of cancer cells to chemotherapeutic agents." (PMID 25675296, 2015). "Importantly, transcriptomics analysis of the screened 941 cancer cell lines revealed that high AXL and TYRO3 mRNA levels predict both resistance to necroptosis and low RIPK3 mRNA levels, but not those of RIPK1, MLKL, or any other pro-necroptotic genes." (PMID 30157175, 2018).
infection (99 papers, 2012 to 2026). The state of being infected such as from the introduction of a foreign agent such as serum, vaccine, antigenic substance or organism. "Uncontrolled RIPK1 kinase activity causes pyroptosis which is essential for the host to control Y. pseudotuberculosis infection in a mouse infection model." (PMID 39883598, 2025). "Our capture of both short- and long-term results of RIPK1 knockdown relatively represent the complex and lengthy degeneration process, which in turn seems to be associated with inflammation and infection." (PMID 31029152, 2019). "In contrast to sterile inflammation, infection-induced type I IFNs induced RIPK1-dependent loss of hematopoietic progenitors." (PMID 30080899, 2018). "Neutrophil release of IL-1β was implicated in RIPK1-dependent ETI in a mouse infection model." (PMID 39883598, 2025). "Interestingly, either murine or human RIPK1 was able to promote the ZBP1-RIPK3 association in human cells, as HSV-1(ICP6mut) infection triggered cell death in RIPK1 KO cells reconstituted with either human or mouse RIPK1." (PMID 39345610, 2024). "WT mice exhibit profound rescue of HSCs and HSPCs upon RIPK1 antagonism with Nec-1s, similar to what is observed in Ifnar1-/--deficient mice, consistent with a central role for RIPK1 kinase activity in the demise of the hematopoietic compartment in IOE infection." (PMID 30080899, 2018). "This places both RIPK3 and RIPK1, critical regulators of necroptosis, at the center of determining cell fate during pathogen infection." (PMID 40434815, 2025). "Even infection with the RIPK1-activating pathogen, Yersinia pseudotuberculosis, results in enhanced RIPK1–caspase-8 activation and enhanced secondary NLRP3 activation." (PMID 40053580, 2025). "Our analysis revealed that phosphorylation at these sites increased immediately after infection, further supporting the inhibition of RIPK1-mediated cell death pathways." (PMID 40607949, 2025). "Macrophage recruitment remained mostly unchanged, but their total numbers increased under both basal and infection conditions following Ripk1 inhibition, indicating that necroptosis is critical for macrophage elimination by ST." (PMID 41360763, 2025). "We observed that caspase-8 was inhibited throughout the infection, and the necroptosis pathway was also suppressed due to the inhibition of phosphorylation and activation of RIPK1, RIPK3, and MLKL, mediated by the TNFα and NF-κB signaling pathways." (PMID 40607949, 2025). "Although RIPK1 kinase-mediated necroptosis can function as a defense mechanism during infections, necroptosis contributes to inflammation seen in murine models of inflammatory diseases." (PMID 41019071, 2025). "This highlights RIPK1’s dual role in antiviral defense and immunopathology, depending on the context of infection and regulatory balance." (PMID 41019071, 2025). "Intriguingly, S25 phosphorylation is described as a pro-survival checkpoint in TNF signaling, as it has been shown to confer resistance to RIPK1-mediated cell death by preventing RIPK1 auto-activation in murine models of infection and inflammation." (PMID 41315176, 2025). "We found here that in a macrophage infection model with the RIPK1-activating pathogen, Y. pseudotuberculosis, the cell death is RIPK1 driven, yet TBK1/IKKε inhibition also sensitizes cells to enhance secondary NLRP3-dependent caspase-1 activation." (PMID 40053580, 2025). "RIPK1-mediated signaling pathways facilitate the clearance of infections by promoting inflammatory responses and cell death mechanisms that limit pathogen spread." (PMID 41019071, 2025). "RIPK1 degradation with R1-ICR-3 also reduced MLKL phosphorylation during HSV-1(ICP6mut) infection in both HS68 and HFFs." (PMID 39345610, 2024). "Here, we show that RIPK1 is crucial for ZBP1-driven cell death triggered in human cells during HSV-1(ICP6mut) infection, where it facilitates the assembly of a stable ZBP1-RIPK3 amyloid complex." (PMID 39345610, 2024).
infection (continued). "Upon infection with Yersinia, RIPK1 promotes caspase-3–dependent GSDME activation, leading to neutrophil pyroptosis." (PMID 38195694, 2024). "In murine models of infection, Yersinia blockade of NF-κB signaling triggers cell-extrinsic apoptosis through Receptor Interacting Serine-Threonine Protein Kinase 1 (RIPK1) and caspase-8, which is required for bacterial clearance and host survival." (PMID 39186805, 2024). "RIPK1 is known to be involved in regulating necrosis, a type of programmed cell death triggered by certain stimuli, such as infection or tissue damage." (PMID 38880876, 2024). "Infection with RVA was shown to activate receptor-interacting protein kinase 1 (RIPK1), RIPK3, and mixed-lineage kinase domain-like protein (MLKL), in infected cells, contributing to the necroptosis of the cell." (PMID 37243249, 2023). "This demonstrates the critical role played by RIPK3 in phosphorylation of MLKL in human macrophages both constitutively and in response to infection and a smaller role for RIPK1 in response to infection." (PMID 37000865, 2023). "In the study, we found that LncRNA NR_003508 functioned as a miR-346-3p sponge to positively regulate RIPK1 expression, which promotes programmed necrosis and infection persistence." (PMID 37175724, 2023). "The results showed that the expression of p-RIPK1/RIPK1, p-RIPK3/RIPK3, and p-MLKL/MLKL was increased with H37Rv infection, while si-NR_003508 effectively reduced the expression of p-RIPK1/RIPK1, p-RIPK3/RIPK3, and p-MLKL/MLKL." (PMID 37175724, 2023). "Compared with the wild-type MCMV (MCMVWT), the M45 mutant MCMV (MCMVM45mutRHIM) infection-induced RIPK3-dependent but RIPK1/TRIF-independent necroptosis and show weaker replication in 3T3-SA or SVEC4-10 cells." (PMID 36142136, 2022). "Serine/Threonine phosphorylation of RIPK1 is known to suppress RIPK1 kinase-mediated cell death in the contexts of inflammation, infection and embryogenesis, however, regulation by tyrosine phosphorylation has not been reported." (PMID 36329033, 2022). "In the setting of pathogens infection, RIPK1 is an important member of the ZBP1-PANoptosome and the key to ZBP1-mediated PANoptosis." (PMID 36142136, 2022). "Contrary to that, expression levels of MAPK14 and RIPK1 were significantly reduced at 24h after infection with any of the viruses." (PMID 36298696, 2022). "Activation of CASP8 is tightly regulated by RIPK1, which showed decreased expression levels in response to infection with either isolate." (PMID 36298696, 2022). "The full length RIPK1 expression gradually declined following day 2 post-infection until day 8 post-infection." (PMID 34824340, 2021). "During infection with wild type EPEC we detected RIPK1 peptides containing either hexose or HexNAc modification of Arg603." (PMID 34133469, 2021). "Our datasets confirm several previously demonstrated PTMs that occur in response to infection, such as elevated phosphorylation of RIPK1 at S321, XIAP at S429 or IRF3 on multiple sites." (PMID 34085925, 2021). "We next examined the role of RIPK1 in mediating inflammation upon infection of lung organoid culture by SARS-CoV-2." (PMID 34663909, 2021). "In conclusion, we have extended our previous findings to show that the cleavage of RIPK1 occurs in infection by many strains of RV, and 3Cpro is the mediator in all cases." (PMID 34960671, 2021). "We also confirmed that NleB2 catalysed arginine-hexose modification of Flag-RIPK1 during infection of HEK293T cells with EPEC E2348/69." (PMID 34133469, 2021). "If the overall effect of RIPK1 is to inhibit infection, RIPK1 becomes an attractive target for inhibition by viruses, especially due to the fact that many signaling pathways can be blocked simultaneously." (PMID 34372694, 2021). "Herein, we show that infection of macrophages with HIV-1 CS204 or with HIV-HSA caused downregulation and cleavage of RIPK1." (PMID 34824340, 2021).
infection (continued). "While not differentially expressed per our definition of two-fold change and FDR less than 0.05, RIPK1 increased highly significantly (FDR = 8 x 10-30) by 1.5-fold post-infection." (PMID 33968035, 2021). "When Triton-X-soluble fractions were evaluated, levels of unprocessed CASP8 (p55), cFLIPL (p55), and RIPK1 (p75) all increased during infection with either virus." (PMID 33126536, 2020). "CASP8, as well as cFLIPL and RIPK1, emerge to be central cell autonomous innate pathogen sensors such that levels of all these proteins increase during infection." (PMID 33126536, 2020). "Although modification of TRADD, FADD, and RIPK1 in in vitro reconstitution system and ex vivo epithelial cell infection system has been studied, the in vivo substrate preference of NleB remains elusive." (PMID 32766249, 2020). "We therefore report on a precise molecular mechanism controlling the switch between RIPK1 pro-survival and pro-death functions and demonstrate its physiological relevance in mouse models of infection and inflammation." (PMID 30988283, 2019). "In a shock-like infection induced by a virulent ehrlichial pathogen, IFNα/β-induced BM failure and hematopoietic suppression via increased RIPK1 activation and diminished caspase 8 expression." (PMID 30080899, 2018). "To control bacterial growth and evaluate the impact of RIPK1 on hematologic recovery from shock-like infection, we administered antibiotics (doxycycline; doxy) in conjunction with Nec-1s to WT IOE-infected mice." (PMID 30080899, 2018). "Yet, in HRV-A16 infection the RIPK1 complex was substantially altered due to 3Cpro, and consisted of the 60 kDa RIPK1 fragment, procaspase-8, 3ABC and/or active 3Cpro and p62/SQSTM1." (PMID 29449668, 2018). "TNFα induces pathology in IOE infection, and TNFα is a driver of necroptotic cell death, a form of programmed necrosis involving RIPK1, RIPK3, and the effector protein MLKL." (PMID 30080899, 2018). "The impairment of dsRNA-induced apoptosis late in infection was controlled by the viral 3C-protease (3Cpro), which disrupted RIPK1-TRIF/FADD /SQSTM1 immune-complexes." (PMID 29449668, 2018). "Addition of TNFα to the cultures following infection induced an additional proportion of cell death that was inhibited by Nec-1, demonstrating RIPK1-dependent cell death in both cell lines in the combined presence of TNFα and M. tuberculosis infection." (PMID 28892415, 2017). "They demonstrate that during infection of macrophages with virulent M. tuberculosis, a complex of RIPK1/RIPK3/pro-caspase-8 translocates to the mitochondria." (PMID 28892415, 2017). "Although we cannot exclude the possibility that PR delivered by virions at the time of infection can cleave RIPK1, our results indicate that the majority of RIPK1 cleavage occurs due to post-integration expression of proviral genes." (PMID 26297639, 2015). "RIPK1 function was shown do be essential for activation of the NLRP3 inflammasome upon infection with RNA viruses, such as Sendai virus or Influenza A." (PMID 26297639, 2015). "This suggests that while RIPK1 kinase activity may be partially activated in the early stages of infection, the recruitment of inhibitory kinases ultimately prevents RIPK1-mediated host cell death." (PMID 40607949, 2025). "To determine whether necroptosis contributes to macrophage elimination during ST infection, we inhibited Ripk1 using necrostatin-2." (PMID 41360763, 2025). "Interestingly, auto-phosphorylation of RIPK1, a key initiator of RIPK1 signaling that promotes apoptosis and necroptosis, was observed as early as 3 hours post-infection." (PMID 40607949, 2025). "This suggests that Rickettsia employs mechanisms to suppress RIPK1-dependent cell death pathways, ensuring host cell survival during the early and middle stages of infection while ultimately relying on RIPK1-independent apoptosis for host cell death in the late stages." (PMID 40607949, 2025).
infection (continued). "As an essential component of host defense against infection, necroptosis is a novel highly regulated mode of cell death that is mediated by signaling complexes containing receptor-interacting protein kinase 1 (RIPK1) and RIPK3." (PMID 38100396, 2024). "RIPK1 is recruited to the ZBP1-RIPK3 complex in human cells during HSV-1(ICP6mut) infection." (PMID 39345610, 2024). "Necroptosis is a form of modulated necrosis that is stimulated downstream of TNFR1; relies on the activity of RIPK1 and RIPK3; is mediated by the mixed-lineage pseudokinase MLKL; and may be caused by mechanical damage, inflammation, or infection." (PMID 36632211, 2023). "Interestingly, recent studies also uncovered mechanisms in which RIPK3 triggers RIPK1-dependent apoptosis, often as part of the induction of multiple regulated cell death pathways in parallel in response to infection." (PMID 36040212, 2022). "Infection with an engineered MCMV variant with a mutational disruption of the viral M45 RHIM domain core tetrad led to ZBP1- and RIPK3-dependent but RIPK1-independent necroptosis, which emphasizes the enormous contribution of this protein to immune evasion and latent infection." (PMID 36040212, 2022). "Then, we asked whether the specific RIPK1 inhibitor necrostatin-1 could prevent the cell death induced by PRV GD-WH infection." (PMID 34149651, 2021). "To determine whether the results that were seen for RVA-16 previously were applicable to other RV strains, we investigated RIPK1 cleavage in infection." (PMID 34960671, 2021). "Physiologic extracellular signals that initiate RIPK1-mediated signaling could differ between in vivo and in vitro infection." (PMID 34372694, 2021). "Finally, given that full-length RIPK1 is decreased during HRV16 infection, it would be interesting to learn if RIPK1-mediated innate immune signaling such as NF-κB and MAPK pathways are disrupted during HRV infections." (PMID 34372694, 2021). "Consequently, pathogens, including viruses, target RIPK1 to evade host immune responses and thereby to establish effective infections." (PMID 34372694, 2021). "The cleavage of RIPK1 may subvert apoptosis specifically, however, the means by which the cells proceed through programmed, or infection-induced cell death remains inconclusive." (PMID 34960671, 2021). "However, mice with a genetic defect in RIPK1 kinase activity (RIPK1KD/KD) had higher viral titers in whole-brain homogenates upon infection with ZIKV." (PMID 34372694, 2021). "Having shown previously that 3Cpro is the major mediator of RIPK1 cleavage in RVA-16 infection, we sought to confirm whether this was consistent amongst other RV strains." (PMID 34960671, 2021). "RIPK1 has been reported to be cleaved by HIV-1 PR during infection." (PMID 33986734, 2021). "Considering that NleB could modify the DDs of TRADD, FADD, and RIPK1 in cell culture infection system, it is necessary to determine the target in vivo." (PMID 32766249, 2020). "When the insoluble fraction was examined, RIPK1 was elevated following infection with either virus." (PMID 33126536, 2020). "Nevertheless, RIPK1 kinase-dependent cell death has revealed its importance in the context of host-pathogen interactions, where it can either participate in the control of infection or favor it5–8." (PMID 30988283, 2019). "Indeed, infection with the vaccinia virus (VV), a poxvirus strain, sensitizes the cells to TNF- induced necroptosis, while the RIPK1 or RIPK3 deficient cells are resistant to the TNF-induced necroptosis." (PMID 31509938, 2019). "Furthermore, to verify the corynebacteria-induced cell death, the attenuation of the necroptosis was determined by treating the cells with the inhibitor of receptor-interacting protein kinase 1 (RIPK1) prior to infection." (PMID 31443569, 2019).